BMP4 (bone morphogenetic protein 4)
Diseases named in the same sentence as BMP4 in open-access papers (continued):
Sharing a sentence is not in itself a finding about the gene and the disease.
Hypertension (24 papers, 2015 to 2026). The presence of chronic increased pressure in the systemic arterial system. "A study on middle-aged Finnish men found a significant association between the BMP2 gene variant (rs235756) and the BMP4 gene variant (rs4901417) were associated with hypertension." (PMID 39997941, 2025). "The rs17563 polymorphism is associated with elevated serum BMP4 levels, which contribute to vascular calcification, endothelial dysfunction, and inflammation, all linked to hypertension." (PMID 39997941, 2025). "Significant interactions were observed between the BMP2 rs1005464 and BMP4 rs17563 polymorphisms, influencing hypertension risk." (PMID 39997941, 2025). "In the meanwhile, deficiency of BMP4 also aggravates Ang II (angiotensin II) -induced hypertension and vascular remodeling in ApoE–/– mice." (PMID 36457800, 2022). "An association between genetic variants in the genes HFE, HJV, BMP4 and arterial hypertension has been shown earlier." (PMID 35442992, 2022). "Previously, we have shown an association between genetic variants of HFE, HJV, BMP4 and arterial hypertension." (PMID 35442992, 2022). "Taken together, these data demonstrated that deficiency of BMP4 in PVAT aggravated Ang II-induced hypertension and vascular dysfunction." (PMID 36457800, 2022). "Overproduction of BMP4 is pro-inflammatory in vascular cells and has been linked to hypertension and increases ID1 expression." (PMID 32759460, 2020). "Additionally, both multiplicative and additive interactions between high fluoride exposure and the BMP4 rs17563 polymorphism were identified, highlighting the combined impact of environmental and genetic factors on hypertension." (PMID 39997941, 2025). "BMP2 gene polymorphisms affect the risk of hypertension, and BMP4 gene polymorphisms may modify the impact of fluoride on hypertension." (PMID 39997941, 2025). "Additionally, an interaction was discovered between the BMP2 rs1005464 polymorphism and the BMP4 rs17563 polymorphism in relation to hypertension." (PMID 39997941, 2025). "We demonstrated that mice with deficiency of BMP4 in PVAT aggravates hypertension development." (PMID 36457800, 2022). "Supporting this hypothesis, independent studies have shown that BMP4 and sEng have in common their involvement in hypertension, a hallmark of preeclampsia a disease associated with increased sEng levels." (PMID 32316263, 2020). "Furthermore, UF and the BMP4 rs17563 polymorphism have an interaction on hypertension." (PMID 39997941, 2025). "Our study demonstrated that interactions between rs17563 (BMP4) and rs235756 (BMP2) influence hypertension risk." (PMID 39997941, 2025). "More recently, adipose-tissue specific knockout of Bone Morphogenetic Protein 4 (BMP4) in apolipoprotein E (ApoE) knockout mice gave rise to high levels of angiotensinogen, angiotensin II, and ROS, resulting in hypertension development." (PMID 37190105, 2023). "These indicates that BMP4 in PVAT has a protective role in hypertension development via regulating local RAAS." (PMID 36457800, 2022). "To evaluate the role of PVAT-derived BMP4 in hypertension, we measured the BP of two types of BMP4-DKO mouse models." (PMID 36457800, 2022). "To further clarify the role of PVAT-derived BMP4 in the pathogenesis of hypertension, we treated two types of BMP4-DKO mouse with Ang II or PBS to generated Ang II–induced hypertensive model." (PMID 36457800, 2022). "This BMP4/ROS/COX-2 cascade constituted a crucial function in the maintenance of endothelial dysfunction in hypertension." (PMID 36359402, 2022). "Taken together, these data suggest that local RAAS is important to the hypertension-protective effect of PVAT-derived BMP4." (PMID 36457800, 2022). "A recent study elegantly demonstrated a potential role of BMP-4 in sEng-mediated perturbation of TGF-β signaling that leads to hypertension." (PMID 34195300, 2021).
Hypertension (continued). "Recently, it was demonstrated that sEng regulates bone morphogenetic protein-4 (BMP4) levels, resulting in the induction of arterial hypertension in mice and cardiac hypertrophy/heart failure, which suggests BMP4 as a downstream mediator of sEng." (PMID 34940528, 2021). "Chronic infusion of BMP-4 induces endothelial dysfunction and hypertension, and treatment with the BMP antagonist, matrix Gla protein, and BMP inhibitors prevents the development of ATS." (PMID 34103026, 2021). "Nevertheless, the present study suggests that BMP4 mediates HS-induced endothelial dysfunction and hypertension." (PMID 33194000, 2020). "We wanted to test the role of BMP4 in mediating high salt-induced ENaC activity in endothelial cells, because previous studies have shown that administration of BMP4 induces hypertension in mice." (PMID 33194000, 2020). "Infusion of BMP4 induced vascular nicotinamide adenine dinucleotide phosphate oxidases and impaired vasodilation, leading to hypertension." (PMID 29596467, 2018). "BMP4 infused chronically results in hypertension and is considered as a novel mediator of endothelial dysfunction and hypertension." (PMID 27642495, 2016). "Here, the rat model of hypertension resulting from two-kidney one-clip (2K1C) model is used to verify the effect of H2S on BMP4/COX-2 pathway and EDCs in renal artery." (PMID 27642495, 2016). "Additional reports suggest roles for BMP4 in endothelial cell dysfunction, inflammation, and hypertension." (PMID 25591903, 2015). "Given that BMP4 contributes to endothelial dysfunction, sEng-BMP4 may be an interesting target for hypertension therapeutics." (PMID 38519450, 2024). "BMP4 deficiency in PVAT promotes vascular remodeling and hypertension by activation of local RAAS." (PMID 36457800, 2022). "To test this hypothesis, we used apolipoprotein E deficient (ApoE–/–) mice with adipose tissue BMP4 knockout or brown adipose tissue BMP4 knockout to examine effects of impaired PVAT metabolism on the development of hypertension." (PMID 36457800, 2022). "Here, we used two different BMP4 knockout mouse models (in adipose tissue or BAT) to examine whether changes of PVAT metabolism, regulated by BMP4, could have an effect on hypertension development." (PMID 36457800, 2022). "In addition, we postulated that the sEng-induced effect in hypertension was mediated by an upregulation of bone morphogenetic protein 4 (BMP4)." (PMID 33375253, 2020). "Interestingly, we recently described that sEng induced the expression of BMP4 which, in turn, mediated the sEng-dependent effect in hypertension." (PMID 33375253, 2020). "We favour the notion that increased BMP4 is a reason for rather than a result of hypertension, because the administration of BMP4 causes hypertension." (PMID 33194000, 2020). "In addition, after crossing female wild type with male sEng+ mice, hypertension appeared 18 days after mating, coinciding with the appearance of high plasma levels of BMP4." (PMID 32316263, 2020). "In contrast to TGF-β which causes endothelial dysfunction in SD rats in response to a relatively high salt (8%) diet, our data suggested that BMP4 may be a signaling molecule that mediates HS-induced hypertension specifically in SS populations." (PMID 33194000, 2020). "Our results demonstrate that H2S prevents activation of BMP4/COX-2 pathway in hypertension, which may be involved in the ameliorative effect of H2S on endothelial impairment." (PMID 27642495, 2016). "Taken together, our present results demonstrate the inhibitory effect of H2S on BMP4 mediated cellular signaling cascade in hypertension, which may be involved in the ameliorative effect of H2S on endothelial dysfunction." (PMID 27642495, 2016).
Hypertension (continued). "BMP2 and BMP4 are particularly important in vascular smooth muscle cell (VSMC) trans-differentiation, a process that leads to the loss of muscle characteristics, increased expression of bone-related proteins, and vascular calcification, all of which are linked to hypertension." (PMID 39997941, 2025). "Our results suggest that BMP4 may contribute to high salt-induced hypertension in SS rats." (PMID 33194000, 2020). "Knockout of BMP4 either in adipose tissue or specifically in BAT aggravates high-fat diet (HFD, 40% fat)-induced hypertension and endothelial dysfunction in ApoE–/– mice." (PMID 36457800, 2022). "A recent study showed the role of BMP-4 in sEng-mediated perturbation of TGF-β signaling and a potential role of this cascade in initiation of hypertension." (PMID 34195300, 2021). "A recent study demonstrated the important role of BMP-4 in perturbation of TGF-β signaling and induction of hypertension." (PMID 34195300, 2021). "Additionally, overexpression of BMP4 may mediate hypertension in patients with colorectal adenocarcinoma, because previous studies have shown that BMP4 is overexpressed in human colorectal adenocarcinoma cells and that hypertension often occurs in patients with adenocarcinoma." (PMID 33194000, 2020). "In mice with BMP4 (bone morphogenetic protein 4 belonging to the TGF-beta superfamily) knockout in perivascular fat, high fat diet-induced hypertension is potentiated by reduced NO release and increased reactive oxygen species production, which enhances vasoconstriction and endothelial dysfunction." (PMID 38186879, 2024). "Apolipoprotein E (ApoE) knockout mice with BMP4 knockout in adipose tissue or brown adipose tissue (aP2-DKO or UCP1-DKO, respectively) were used for exploring the role of impaired PVAT metabolism in hypertension." (PMID 36457800, 2022). "Since overexpression of BMP-4 in endothelial cells enhances vascular remodeling in pulmonary hypertension it cannot be excluded that higher serum levels of BMP-4 can contribute to the vascular abnormalities frequently observed in the C group (e.g., telangiectasia, PAH and arterial hypertension)." (PMID 39697336, 2024). "Thus, we hypothesized that BMP4 in PVAT is a critical mediator to maintain PVAT metabolism and protects against hypertension." (PMID 36457800, 2022). "Moreover, sEng-induced hypertension was absent in the presence of the BMP4 inhibitor–noggin, suggesting that BMP4 is a downstream regulator of sEng." (PMID 33808559, 2021). "Therefore, we hypothesize that H2S can downregulate BMP4/COX-2 pathway, which may be involved in ameliorating endothelial dysfunction in hypertension." (PMID 27642495, 2016).
prostate carcinoma (23 papers, 2006 to 2025). A carcinoma that arises from epithelial cells of the prostate gland. "Although the bone forming phenotype in prostate cancer, bioinformatics analysis of the mutations identified as pathogenic in BMP4 and exposed that both osteoblastic and osteolytic lesions are present in the same loci." (PMID 29719616, 2018). "One neutral single nucleotide polymorphism p.S38S (score 0.15) was found in BMP2 and one pathogenic mutations causing prostate cancer, p.T214T was identified in BMP4." (PMID 29719616, 2018). "We identified one pathogenic mutation, p.T214T in BMP4, causing prostate cancer and one neutral mutation p.S38S in BMP2." (PMID 29719616, 2018). "Furthermore, treatment of carcinoma-associated fibroblasts (CAFs) derived from a mouse prostate carcinoma with BMP4 was shown to stimulate angiogenesis." (PMID 23840733, 2013). "It is also known that prostate cancer cells secreting higher levels of BMP4 exhibit enhanced bone formation in vivo." (PMID 36552843, 2022). "For exploring the impact of these somatic substitution mutations in the selection region on human cancer, we identified one pathogenic mutation in human BMP4 and one in BMP15, possibly causing prostate cancer and six neutral mutations in BMPs." (PMID 29719616, 2018). "BMP4 plays an important role in bone metastasis of prostate cancer, and BMP4 overexpression inhibits proliferation and induces apoptosis in many cancer cell line." (PMID 22537906, 2012). "BMP4 has also been shown to inhibit growth of the prostate cancer cell line LNCaP and induce the expression of ID1, ID2, and ID3 in cell lines." (PMID 16638148, 2006). "Larger studies will be necessary to definitively establish whether BMP4 expression has independent prognostic value in advanced prostate cancer." (PMID 40593552, 2025). "Furthermore, in vivo research has emphasized BMP4's role in bone formation within a xenograft model of prostate cancer bone metastasis." (PMID 40304052, 2025). "Moreover, findings from in vivo studies have underscored the involvement of BMP4 in osteogenesis within a xenograft model of prostate cancer bone metastasis." (PMID 38049682, 2023). "We previously reported that BMP-4 induces the production of sonic hedgehog in prostate cancer cells, thereby enhancing osteoblastic differentiation of stromal cells and may account for osteoblastic metastasis of prostate cancer." (PMID 35693928, 2022). "BMP4 has been shown to promote prostate tumor growth in bone by stimulating osteogenesis and, specifically, to stimulate endothelial to osteoblast conversion leading to osteoblastic bone formation in prostate cancer patients." (PMID 29670000, 2018). "BMP4 expression has been reported in osteosarcoma, bone fibrous dysplasia, gastric cancer, prostate cancer, and salivary gland tumors, and the expression of this protein may affect the biological behavior of tumors and the disease prognosis." (PMID 24099560, 2013). "In order to clarify whether cathepsin H also regulates BMP-4 in humans, its impact on BMP-4 expression, processing and degradation was investigated in prostate cancer (PC-3), osteosarcoma (HOS) and pro-monocytic (U937) human cell lines." (PMID 22933963, 2011). "In prostate cancer, HOXD13 binds to the SMAD1 promoter, disrupting BMP4-induced EMT and reducing tumor cell invasiveness." (PMID 39744569, 2025). "In vitro studies have highlighted the combined effect of BMP4 and SHH in supporting the survival of prostate cancer cells and promoting the differentiation of bone stromal cells, which may lead to the osteoblastic metastasis typical of prostate cancer." (PMID 40304052, 2025). "In vitro investigations have illuminated the cooperative impact of BMP4 and SHH on fostering the survival of prostate cancer cells alongside the differentiation of bone stromal cells, potentially culminating in the osteoblastic metastasis characteristic of prostate cancer." (PMID 38049682, 2023).
colon carcinoma (22 papers, 2005 to 2026). "In contrast, colon tumor organoids responded poorly to BMP4 showing only weak signals of cell differentiation, and were unresponsive to DBZ." (PMID 38684650, 2024). "We treated 3D cultures of Caco-2 colon cancer cells with BMP4 protein and it significantly upregulated KLF4." (PMID 36276637, 2022). "We detected more modest inverse correlations with BMP4 and FOSL1 (but with higher conditional R2-values and high p-values); these genes are also implicated in colon cancer cell proliferation and metastasis." (PMID 35370785, 2022). "In contrast, another study showed that BMP4 was involved in the suppression of colon cancer cell growth and that the activated KRAS down-regulated BMP4 via the ERK pathway." (PMID 33982211, 2021). "High levels of Foxa1 expression were observed in poorly differentiated colon cancer, and Gata6, the colon homolog of Gata4, participates in the regulation of stemness by preventing Bmp4-induced differentiation in Wnt-driven colon cancer." (PMID 33349639, 2020). "Gata4/6 transcription factors had previously been reported to repress Bmp4, thereby maintaining colon cancer stemness." (PMID 33349639, 2020). "Similar accumulation of BMP4 in the nucleus has been demonstrated earlier in a small proportion of colon cancer cells." (PMID 30287850, 2018). "Biologically, BMP signaling has been suggested to cause human cancer through its tumor suppressor properties, but colon cancer cells were resistant to the growth suppression and differentiation induced by BMP4." (PMID 29258461, 2017). "In conclusion, our present study reveals that Dragon stimulates colon cancer growth via the BMP4 and the downstream Smad1/5/8 and Erk1/2 pathways both in vitro and in vivo." (PMID 26029998, 2015). "Dragon's action on colon cancer development was mediated via the BMP4-Smad1/5/8 and Erk1/2 pathways." (PMID 26029998, 2015). "More recently BMP-4 has been used as a differentiation agent in controlling colon cancer in mice using models based on CSCs." (PMID 23800258, 2013). "In this review we provide strong support that BMP4 is an innovative therapeutic approach to prevent colon cancer growth increasing differentiation markers expression and apoptosis." (PMID 24212789, 2011). "It has been reported that BMP-4 is overexpressed and secreted by human colon cancer cells with mutant APC genes." (PMID 15785755, 2005). "In a study on the colon cancer, researchers found that KRAS mutations can activate the transcription factor TFCP2, which in turn upregulates the expression of adipogenic factors BMP4 and WNT5B, ultimately inducing CAFs to transform into a special subtype rich in lipids." (PMID 41469334, 2026). "Consistent with our data, it has been shown that the stimulation of LXR could down-regulate β-catenin targets such as Bmp4, Myc, Cyclin D1, and Mmp7 participating in the survival and proliferation of colon cancer cells." (PMID 33568147, 2021). "Dragon-mediated colon cancer cell proliferation is dependent on BMP4." (PMID 26029998, 2015). "Interestingly, increased BMP4 expression has been discerned in the context of Colitis-associated colon cancer relative to nonneoplastic mucosa, underscoring its potential implication in disease progression." (PMID 37628872, 2023). "Additionally, BMP4 has been reported to promote colon cancer cell invasiveness and tumor formation." (PMID 33982211, 2021). "Using three different gene datasets representative of differentiated Caco-2 cells, we found the remaining of well-described colon cancer phenotype markers CD44 and BMP4 in accordance with a poor healthy phenotype restoration." (PMID 28726765, 2017). "BMP-4, a member of the TGF-β super family of secreted proteins has been shown to have potential applications in treating GBM and colon cancer." (PMID 23800258, 2013). "To determine whether Dragon's action on colon cancer requires BMP2 and BMP4, we first examined BMP2 and BMP4 expression in CT26.WT and CMT93 cells." (PMID 26029998, 2015).
colon carcinoma (continued). "Our data show that signaling cues such BMP4 that promote cell differentiation in colon normal organoids do not have similar effects on colon cancer organoids, supporting the notion that oncogenesis is tightly associated to the suppression of cell differentiation." (PMID 38684650, 2024). "Indeed, BMP2, BMP3, BMP4 and BMP7 inhibit proliferation and induce apoptosis and differentiation in colon cancer cells that do not have Smad4 mutation and loss of PTEN." (PMID 24212789, 2011). "To investigate whether calcitriol could modulate cell differentiation in colon tumor organoids cultured under differentiation conditions, we first studied the expression of marker genes in organoid cultures of four patients upon 72 h or 120 h incubation in PROL, BMP4, DBZ or B + D media." (PMID 38684650, 2024). "To investigate whether cancer stem cells present in colon tumor organoids could respond to differentiation stimuli, we studied the expression of marker genes in organoid cultures of four patients upon 72 h or 120 h incubation in PROL-T, BMP4, DBZ or B + D media." (PMID 38684650, 2024).